SIRT1 (sirtuin 1)
Diseases named in the same sentence as SIRT1 in open-access papers (continued):
Sharing a sentence is not in itself a finding about the gene and the disease.
Hyperglycemia (continued). "The tight interconnection between p300 and SIRT1 may regulate accelerated vascular ageing associated with hyperglycaemia." (PMID 36766773, 2023). "Because loss of Sirt1 in the fat body alters glucose metabolism and insulin sensitivity in the organism, we expected modifiers of hyperglycemia to impact pathways linked to central carbon metabolism as well as external processes that influence secretion and signaling of hormones such as insulin." (PMID 35435227, 2022). "Weakened expression of SIRT1 in cultured podocytes isolated from diabetic mice was caused by an increased amount of advanced glycation end products (AGEs) characteristic of long-term hyperglycemia." (PMID 34685718, 2021). "Within expectation, our results showed that BAK treatment reversed the downward trends of SIRT1 expression and Nrf2 nuclear translocation caused by hyperglycemia, while EX527, SIRT1 siRNA, or Nrf2 siRNA abolished this effect, finally nullifying the antioxidative actions of BAK." (PMID 33062139, 2020). "For instance, the downregulation of SIRT1 by hyperglycemia caused vascular dysfunction in DM." (PMID 33304318, 2020). "Metformin may be considered either a direct or LKB-1/AMPK-mediated modulator of SIRT1 expression, able to alleviate hyperglycemia-caused endothelial senescence and cell death." (PMID 33375185, 2020). "Accordingly, we hypothesised that SIRT1 activation would reduce α cell hyperplasia and hyperglucagonaemia as a way of attenuating the insensible energy loss of hyperglycemia in type 1 diabetes." (PMID 30228292, 2018). "In addition, hyperglycemia accelerates endothelial cell senescence which is associated with reduction in SIRT-1." (PMID 27542238, 2016). "However, activating SIRT1 prevents the vascular cell damage caused by hyperglycemia." (PMID 40243583, 2025). "Hence, activation of the AMPK/SIRT1/PGC-1α pathway could be a possible mechanism associated with the therapeutic approach for hyperglycemia-induced renal damage." (PMID 32050658, 2020). "Thus, we hypothesized that ISL could inhibit the hyperglycemia-induced inflammatory and oxidative damages caused by the development and progression of DN by restoring SIRT1." (PMID 33288747, 2020). "Therefore, loss of SIRT-1 may explain hyperglycemia-induced chronic inflammatory responses in the diabetic retina." (PMID 26466127, 2015). "Together these findings suggest an NGF/Sirt1 axis where NGF upregulates Sirt1 to maintain autophagy and cell survival, conversely, hyperglycemia-driven Cdk5 activation suppresses NGF, impairing autophagy." (PMID 41471293, 2025). "Stabilizing SIRT1 activity alleviates ferroptosis in islet β-cells, improves insulin secretion, and mitigates hyperglycemia symptoms." (PMID 40109363, 2025). "Research has shown that hyperglycemia inhibits the expression of SIRT1 in islet β-cells, leading to decreased levels of the antioxidant enzyme GPX4 and increased expression of the ferroptosis-related protein TFR1." (PMID 40109363, 2025). "Activation of the AMPK/SIRT1/PGC-1α signaling pathway by honokiol alleviates hyperglycemia-induced oxidative stress and ferroptosis, thereby improving cell function." (PMID 40109363, 2025). "Astragaloside-IV can enhance SIRT1 and Nrf2 activity, boost cellular antioxidant capacity, reduce hyperglycemia-induced ferroptosis, and protect retinal pigment epithelial (RPE) cells from damage, offering a potential therapeutic strategy for DR." (PMID 40109363, 2025). "Hyperglycemia suppresses lncRNA-MEG3 expression, which normally elevates SIRT1 levels by sequestering miR-34a, thus inhibiting the NF-κB pathway and reducing apoptosis induced by hyperglycemia." (PMID 40589740, 2025). "Increasing evidence suggests that hyperglycemia leads to reduced SIRT1 activity, resulting in increased acetylation of PGC-1α and dysfunction in energy metabolism." (PMID 39335456, 2024). "In diabetic mice, hyperglycemia-induced endothelium senescence is inhibited by SIRT1 activation, protecting against vascular impairment." (PMID 39406930, 2024).
Hyperglycemia (continued). "To identify the biological function of Sirt1, we investigated the effect of Sirt1 overexpression by transfecting pcDNA3.1‐Sirt1 in podocyte apoptosis induced by hyperglycemia." (PMID 38506068, 2024). "Sirt1 overexpression significantly prevented the down‐regulation of nephrin and podocin induced by hyperglycemia." (PMID 38506068, 2024). "It has been shown that formononetin treatment reduces hyperglycemia in pancreatic cells by increasing the levels of Sirtuin 1 (SIRT1), an enzyme that protects cells from ROS-induced damage." (PMID 39062550, 2024). "Certain studies have indicated that hyperglycemia or AGEs inhibit NRF2 activity through the ERK pathway or the NRF2-activating mediator Sirt1." (PMID 39735782, 2024). "Mechanically, hyperglycemia impaired mitochondria through SIRT1/AMPK/PGC1α signaling, resulting in significant cardiomyocyte apoptosis and the release of extracellular vesicles containing mtDNA." (PMID 38790051, 2024). "Another study suggested that miR-155 promoted hyperglycemia-induced podocyte inflammation by targeting SIRT1, leading to impaired renal function and exacerbated renal pathological changes." (PMID 38216907, 2024). "The finding that hyperglycemia reduces SIRT1 expression and speeds up endothelium senescence provided an explanation for similar outcomes." (PMID 39406930, 2024). "Collectively, these results elucidated that up‐regulation of Sirt1 alleviated mitochondrial dysfunction induced by hyperglycemia in podocytes." (PMID 38506068, 2024). "Hyperglycemia aggravates mitochondrial injury through SIRT1/AMPK/PGC1α signaling, resulting in significant cardiomyocyte apoptosis and the release of extracellular vesicles containing mtDNA in DCM mice." (PMID 38790051, 2024). "SIRT1 has been reported to stimulate c-Myc expression by promoting forkhead box protein O1 (FoxO1) degradation, which prevents hyperglycemia-induced endothelial cell dysfunction and angiogenesis." (PMID 38003402, 2023). "Hyperglycemia and hypercholesterolemia also inhibit SIRT1, but curcumin has been shown to restore its activity, acting as a protective agent against ischemia-reperfusion injury." (PMID 37630770, 2023). "The effect of LPS was noticeable 24 h after its administration (time point 24 h) only for hyperglycemia, where the SIRT1 concentration in the BC dropped to 13 pg/μL (6% of its initial value)." (PMID 37511397, 2023). "It is reported that hyperglycemia by increasing fatty acids and through p66Shc enhances miR-34a expression and subsequently decreases SIRT1 expression." (PMID 38129872, 2023). "SIRT1 mutant mice develop progressive hyperglycemia, glucose intolerance, and insulin insufficiency, which directly correlate with SIRT1 deletion." (PMID 36632457, 2023). "This study revealed that hyperglycemia-related oxidative stress can affect the molecules involved in the SIRT1/p66Shc-mediated pathway." (PMID 38129872, 2023). "We detected comparable levels of SIRT1 in the BC for all glycemic backgrounds: 211 pg/μL for hypoglycemia, 197 pg/μL for normoglycemia, and 206 pg/μL for hyperglycemia 24 h after the establishment of different glucose concentrations in the MC." (PMID 37511397, 2023). "The study concludes that SIRT1 is a promising therapeutic target to rescue hyperglycemia‐induced AD." (PMID 36073820, 2022).
Hyperglycemia (continued). "In summary, SIRT1 pathway is required for melatonin to prevent hyperglycaemia-induced impairment of steroidogenesis in Leydig cells." (PMID 35962432, 2022). "Our data provide new evidence for the relationship between melatonin and SIRT1 pathway in the context of hyperglycaemia, which functions to promote steroidogenesis by coordinating mitochondrial biogenesis, mitophagy and redox signalling." (PMID 35962432, 2022). "It has been reported that activation of SIRT-1 prevents hyperglycemia-induced vascular cell senescence and thereby improves vascular function in diabetic conditions." (PMID 36496468, 2022). "Hyperglycemia disrupted the integrity of brain microvasculature and subsequently induced neurodegeneration via decreased SIRT1 expression." (PMID 36073820, 2022). "Further work will therefore be required to determine if CG5888, the top GWA candidate (P = 2.80E-07), is capable of modifying hyperglycemia in the r4>Sirt1-RNAi model, and if so, in which tissues it is acting." (PMID 35435227, 2022). "Resveratrol has been shown to suppress the pro-atherosclerotic effects of hyperglycemia on ECs by limiting ET-1 and E-selectin mRNA expression and boosting endothelial NO synthase via eNOS/NO signaling, which is triggered by SIRT1 activation." (PMID 35742837, 2022). "The negative correlation of ACE2 to T2D is mirrored by the finding that SIRT1 in negatively correlated with hyperglycemia." (PMID 39086962, 2022). "Our observations suggest that activation of PPARδ by a specific ligand attenuates hyperglycemia-triggered premature senescence of RPE cells via upregulation of SIRT1, which reduces cellular ROS accumulation." (PMID 35740104, 2022). "Our results showed that intracellular oxidative stress in hyperglycemia was overexpressed, while FoxO1, SIRT1, GPX1, and SOD2 were downregulated." (PMID 36057883, 2022). "Melatonin treatment ameliorated hyperglycaemia-induced impairment of Leydig cell function with simultaneous stimulation of 5’-adenosine monophosphate activated protein kinase (AMPK)/SIRT1 activity and the expression of autophagy-related genes." (PMID 35962432, 2022). "Melatonin provides protection against hyperglycaemia-induced impairments in steroidogenesis, with simultaneous stimulation of SIRT1 pathway." (PMID 35962432, 2022). "SIRT1 deacetylates H3 histones at the human endothelial p66Shc promoter to suppress the transcription of ROS and promote transcription of SOD; therefore, SIRT1 prevents hyperglycemia-induced endothelial dysfunction and avoids hyperglycemic memory." (PMID 35562979, 2022). "Knockdown of the genes CG4168, CG5888, and uif resulted in suppression of the hyperglycemia phenotype, with a significant decrease in glucose content per fly compared to controls expressing r4>Sirt1-RNAi." (PMID 35435227, 2022). "It has been shown that Sirt1 exerts anti-inflammatory effects and reduces the hyperglycaemia-induced fibrosis of glomerular mesangial cells by promoting the transcriptional activity of the FOXO3 protein." (PMID 36232910, 2022). "The upregulation of SIRT1 by PPARδ is a critical event in the blockade of hyperglycemia-induced premature senescence of ARPE-19 cells." (PMID 35740104, 2022). "Diabetic mice and hyperglycemia-exposed proximal tubule cells treated with the SGLT2 inhibitor canagliflozin exhibited recovered SIRT1 expression both in vivo and in vitro, respectively." (PMID 35277012, 2022). "Hyperglycemia and hypercholesterolemia inhibit SIRT1 and curcumin is able to restore its activity, thus acting as a protective agent against ischemia-reperfusion injury." (PMID 35807694, 2022). "Here, we demonstrate that melatonin mitigates hyperglycaemia-induced impairment of the steroidogenic function of Leydig cells both in vivo and in vitro with simultaneous activation of SIRT1 pathway." (PMID 35962432, 2022).
Hyperglycemia (continued). "Sirt1 RNAi expressed in the fat body (r4>Sirt1-RNAi) reproduces the hyperglycemia phenotype, with an approximately 50–60% increase in whole fly glucose levels (P = 0.02)." (PMID 35435227, 2022). "This study demonstrated that resveratrol protects mesangial cells against hyperglycemia-induced oxidative damage directly or indirectly through SIRT1 activity stimulation." (PMID 35277012, 2022). "Resveratrol, a natural polyphenol, has also been shown to normalize hyperglycemia and hyperlipidemia, improve beta-cell function and insulin sensitivity, and lower hepatic glucose production through the activation of SIRT1." (PMID 34656137, 2021). "In the present study a downregulation in epigenetic marker SIRT1 was apparent in the cells that were exposed to hyperglycemia after 48-h exposure." (PMID 34639171, 2021). "The role of resveratrol contained in red wine as an activator in the SIRT1 prevention of endothelial injuries related to atherogenesis and hyperglycemia stress is, to date, widely described." (PMID 34073604, 2021). "They found that hyperglycemia-induced miR-34a had an anti-angiogenic action in MMECs via downregulation of SIRT1 and eNOS expression." (PMID 34698884, 2021). "SIRT1 activation was found to prevent hyperglycemia-induced endothelial dysfunction via multiple mechanisms." (PMID 34071497, 2021). "And it has been demonstrated that resveratrol can activate the SIRT1-mediated white fat browning pathway and improve hyperglycemia and hyperlipidemia in mice." (PMID 34616289, 2021). "The restriction of the AMPK/SIRT1/PGC-1α axis induced by hyperglycemia led to mitochondrial injury of Schwann cells and subsequently resulted in demyelination changes and axonopathy." (PMID 33746703, 2021). "SIRT1 activation also protects against hyperglycemia-induced renal tubular damage via the deacetylation of FOXO3a and the reduction of oxidative stress in vivo and in vitro." (PMID 35222012, 2021). "SIRT1 activation is induced by increased ionized NAD, and conversely a shift in the NADH/NAD+ ratio, commonly observed in hyperglycemia, decreases SIRT1 expression, potentially leading to detrimental effects in the cell." (PMID 34639171, 2021). "A study demonstrated that Sirt1 inhibits hyperglycemia-induced renal inflammation by negatively regulating the NLRP3 inflammasome in DM." (PMID 35096293, 2021). "Senescence is a major contributor to aging and the development of cardiovascular disease, and sirtuin-1 expression is required for metformin to protect endothelial cells against hyperglycemia-induced senescence." (PMID 34421827, 2021). "Arunachalam and colleagues investigated in mouse microvascular endothelial cells (MMECs) the molecular crosstalk between miR-34a, SIRT1 and the antidiabetic drug, metformin, in hyperglycemia-mediated impaired angiogenesis." (PMID 34698884, 2021). "Increased accumulation of acetylated FOXO4 has been demonstrated as a result of decreased SIRT1 activity in podocytes in the course of hyperglycemia in diabetic kidney disease." (PMID 34685718, 2021). "Formononetin protects diabetic animals from hyperglycemia-induced neuronal damage by increasing the expression of SIRT1 and NGF in neural tissue." (PMID 34159207, 2021). "2,6-diisopropylphenol (propofol) has been found to reciprocate hyperglycemia-triggered P66shc activation in human umbilical vein endothelial cells through SIRT1 activation and can prevent endothelial ROS accumulation, inflammation, and apoptosis." (PMID 34071497, 2021). "It has been proved that expression of PPARα was reduced by hyperglycemia, and SIRT1 activated PPARα pathway to reduce ROS in diabetic vascular diseases." (PMID 33304318, 2020).
Hyperglycemia (continued). "The SIRT1-PGC-1α-HO-1 axis is vital in the reduction of oxidative stress by hyperglycemia and protection of the diabetic heart." (PMID 32952955, 2020). "Our previous studies showed that CHS protected hyperglycemia-induced myocardial injury by activating the SIRT1/ERK1/2/Homer1a pathway." (PMID 31969494, 2020). "Activation of the Nrf2- antioxidant response element (ARE) antioxidative pathway ameliorates hyperglycemia-mediated mitochondrial dysfunction partly through Sirt1." (PMID 32774664, 2020). "In a recent study, resveratrol has been shown to decrease hyperglycemia-induced injury to cardiomyocytes by increasing mitochondrial biogenesis via the SIRT1-PGC-1α pathway." (PMID 32674299, 2020). "Intriguingly, in recent years, SIRT1 has attracted widespread attentions as a protein modulator and stress adaptor related to hyperglycemia attenuating cardiac dysfunction and improving diabetic cardiomyopathy." (PMID 33062139, 2020). "We demonstrated hyperglycaemia exposure led to the up-regulation of miR-204 and down-regulation of SIRT1 in ARPE-19 and PRPE cells." (PMID 31894851, 2020). "Flavonoid compounds are effective in mitigating hyperglycemia-induced diabetic complications by enhancing the expression of the sirtuin family, with the silent information regulator 2 homolog 1 (SIRT1) in particular, as shown in more and more studies." (PMID 33288747, 2020). "Resveratrol reduces hyperglycemia-induced oxidative stress damage by modulating SIRT1 deacetylase activity and the SIRT1/FOXO3a pathway." (PMID 31935891, 2020). "Hyperglycemia, inflammation, oxidative stress, and hypertension induce renal inherited cellular senescence and the downregulation of antiaging proteins, such as Sirt1 and Klotho, and the inactivation of the lysosome-dependent autophagy pathway." (PMID 32774664, 2020). "Oxidative stress and downregulated AMPK/SIRT1 signaling pathway can directly and indirectly activate NF-κB in hyperglycemia." (PMID 32050658, 2020). "SRT1720 was found to markedly raise SIRT1 expression in hyperglycaemia-induced podocyte EMT and that EX527 abolished the effects of AS-IV." (PMID 30674969, 2019). "Another study showed that fenofibrate regulated hyperglycemia-induced metabolic memory via SIRT1-dependent suppression of NF-κB in human retinal endothelial cells." (PMID 31299012, 2019). "It has been reported that SIRT1 activation attenuates hyperglycemia and plays an important mediatory role in treating diabetic complication." (PMID 31481873, 2019). "Collectively, these finds demonstrated the therapeutic potential of THC treatment to alleviate DCM mainly by attenuating hyperglycemia-induced oxidative stress and fibrosis via activating the SIRT1 pathway." (PMID 31210844, 2019). "Sirt1 has been previously recognized to protect endothelial cells against hyperglycemia-induced oxidative stress and apoptosis." (PMID 30863684, 2019). "Since this study and others have demonstrated an inverse correlation between the diabetic environment and reduced SIRT1 levels, a high glucose in vitro model was used to compare the direct effect of hyperglycaemia vs osteogenic conditions on SIRT1 production." (PMID 30696833, 2019). "Maternal hyperglycemia increased the expression of histone acetylase P300, but decreased the expression of the histone deacetylase SIRT1." (PMID 30824686, 2019). "SIRT1 activation is induced by increased ionised NAD, and conversely a shift in the NADH/NAD + ratio, commonly observed in hyperglycaemia, decreases SIRT1 expression, potentially leading to detrimental effects in the cell." (PMID 30696833, 2019). "In the present study, we demonstrated that hyperglycemia decreased Sirt1, total FOXO3a protein levels and phos-FOXO3a Ser318/321." (PMID 31406124, 2019). "SIRT1 activator suppresses hyperglycemia-induced apoptosis of podocytes via autophagy activation in diabetic mice with nephropathy." (PMID 31321239, 2019).